LINC02500 (long independently transcribed non-coding RNA 2500)
Gene: Long non-coding RNA gene on chromosome 4 (181,260,442 to 181,265,148, reverse strand). Ensembl gene ENSG00000249460.
Diseases named in the same sentence as LINC02500 in open-access papers:
LINC02500 is named in the same sentence as 2 diseases in open-access papers, as found by Europe PMC text mining. Sharing a sentence is not in itself a finding about the gene and the disease. The quoted sentences say what the papers report.
cervical cancer (1 paper, 2022). A primary or metastatic malignant neoplasm involving the cervix. "Combined with the corresponding RNA-seq data, we highlight LINC00290, LINC02500, and LENG9 as potential driver genes for cervical cancer." (PMID 35538075, 2022). "Combining this with the corresponding RNA-seq data, we were able to pinpoint LINC00290, LINC02500, and LENG9 as potential driver genes in cervical cancer." (PMID 35538075, 2022). "Combined with the corresponding RNA-seq data, we highlighted LINC00290, LINC02500, and LENG9 as potential driver genes in cervical cancer." (PMID 35538075, 2022). "Combined with the corresponding RNA-seq data, we highlight LINC00290, LINC02500 and LENG9 as potential driver genes in cervical cancer." (PMID 35538075, 2022).
tumor (1 paper, 2022). "However, our current large-range high-resolution results suggest the recently annotated LINC02500 may be a tumor suppressor candidate gene, while LINC00290 may be an oncogene candidate gene." (PMID 35538075, 2022).